TLR4 (toll like receptor 4)
Diseases named in the same sentence as TLR4 in open-access papers (continued):
Sharing a sentence is not in itself a finding about the gene and the disease.
tumor (continued). "We have recently reported that UVB-induced cutaneous carcinogenesis is retarded in TLR4 deficient mice relative to TLR4 proficient mice, and this occurs at least in part via inhibition of suppressor cells that augment pro-tumor responses." (PMID 34771569, 2021). "TLR-4 has also been linked with pro-tumor effects through promotion of angiogenesis and tumor invasion." (PMID 33980266, 2021). "Diminished TLR4 expression is associated with the malignant behavior of tumors (high pathological grade, higher tumor stage, and progression)." (PMID 34141706, 2021). "In pancreatic cancer, TLR4 activity can promote EMT through M2-polarized tumor-associated macrophages." (PMID 33554122, 2021). "Consistent with this, sophoridine has been shown to polarize tumor-associated macrophages (TAMs) into M1-TAMs and suppress M2-TAMs polarization through the TLR4/IRF3 axis." (PMID 34646828, 2021). "In tumor cells, TLR4 has been reported to be highly expressed and is associated with tumor malignancy." (PMID 33628591, 2021). "Recently, a report showed the intersection of TLR4 signaling, epithelial redox activity and the microbiota in colitis-associated neoplasia." (PMID 34299310, 2021). "The results obtained suggest that MLH1 deficiency alters TLR4 mRNA expression both in normal and tumor colonic mucosa." (PMID 34026821, 2021). "In mechanistic studies, S. choleraesuis was found to cause a strong inflammatory response at the tumor site by acting on TLR4 to recruit a variety of immune cells against tumor cells." (PMID 32194422, 2020). "P. anaerobius can also interact with toll-like receptor 2 (TLR2) and TLR4 on colon cells, and modulate myeloid-derived suppressor cells (MDSCs), granulocytic tumour-associated neutrophils and tumour-associated macrophages (TAMs), thus promoting CRC." (PMID 33213502, 2020). "Nab-paclitaxel has also been demonstrated to induce anti-tumour immunity through the reprogramming of tumour-associated macrophages via TLR4 in vitro and in vivo." (PMID 32635552, 2020). "A reduction in the incidence, size, and number of neoplasms induced by chemicals has been observed in TLR4- and MyD88-deficient mice, thus underscoring a supportive role of TLR signaling in hepatocarcinogenesis." (PMID 32012718, 2020). "As a substantial contributor to ICD, HMGB1 activates the immune system by being released from dying tumor cells and prompts the cross-presentation of tumor-associating antigens through its ligation and triggering of TLR4 on dendritic cells (DC)." (PMID 32698492, 2020). "Mice undergoing the sleep disruption protocol had higher numbers of tumor associated macrophages (TAMs) and engagement of TLR4 signaling pathways, suggesting an inflammatory mechanism." (PMID 31174326, 2019). "Their findings suggested that sleep fragmentation can promote tumour growth and advancement via the recruitment of tumour-associated macrophages and pro-inflammatory TLR4 signalling pathway." (PMID 31836779, 2019). "Loss of TLR4 was shown to abrogate DCs’ capacity to present tumor-specific antigens upon treatment of both mice and humans with breast cancer." (PMID 30699928, 2019). "They found that mice deficient for TLR4 featured a decreased ability to resist KP tumor progression." (PMID 31191545, 2019). "Anthracycline chemotherapies induce an immunogenic cell death (ICD) program in tumor cells, including the release of damage-associated molecular patterns (DAMPs), which are subsequently sensed by complementary PRRs, especially TLR4 expressed on DCs." (PMID 31553907, 2019). "In conclusion, our study provides evidence that TLR4 signaling plays a key role in MSC transformation by inducing a pro-tumor phenotype associated with a permissive microenvironment allowing immune escape and tumor growth." (PMID 31541083, 2019). "Accumulating evidence suggested that high expression of TLR4 was associated with the metastasis of tumor and elevated TLR4 expression promotes tumor progression by contributing to metastasis." (PMID 29560134, 2018).
tumor (continued). "PAUF immunoreactivity was significantly associated with high grade (p = 0.014), and TLR4 immunoreactivity was associated with advanced tumor stage (p = 0.002)." (PMID 30111860, 2018). "In this study, we demonstrated that TLR-4 gene deficiency preserved Dkk-3 and claudin-5 expressions and promoted apoptosis process, so determining a slowing of tumor growth." (PMID 30680070, 2018). "Higher tumor burden was demonstrated in APC(Min/+) mice following inoculation of clinical isolates of F. nucleatum, and was associated with activation of TLR4/MyD88/NFκB signaling and recruitment of tumor-infiltrating myeloid cells." (PMID 30413188, 2018). "In the subgroup of tumor type, the association between high TLR4 expression and poor OS was significant, except for NSCLC." (PMID 29560134, 2018). "Mechanistically, MGLL deficiency promotes CB2/TLR4-dependent macrophage activation, which further suppresses the function of tumor-associated CD8+ T cells." (PMID 29968710, 2018). "An association between baseline tumor TLR4 expression by immunohistochemistry (IHC) and clinical response was observed." (PMID 30400835, 2018). "A double mutation of E439G with F703C, representing a tumor with two TLR4 mutations, showed a further decrease in TLR4 signaling compared to F703C (p = 0.0052) but not E439G (p = 0.099)." (PMID 28531216, 2017). "A growing number of studies have reported the key role of TLR4/NF-κB/TNF-α signaling to promote tumor growth in experimental models of colitis associated cancer, whereas data from human CAC are rare." (PMID 28408791, 2017). "This review will summarize the expression and function of TLR4 on dendritic cells (DCs), tumor-associated macrophages (TAMs), T cells, myeloid-derived suppressor cells (MDSCs), tumor cells as well as stromal cells in tumor microenvironment." (PMID 29029545, 2017). "Contemporary studies highlighted a key function of the TLR system in the development of colitis-associated tumor, suggesting TLR4's role in CRC development and progression and its function as a potential prognostic marker of CRC." (PMID 27409669, 2016). "Although chemotherapy-induced HMGB1/TLR4 signaling has primarily been associated with anti-tumor immune responses, HMGB1 has also been shown to promote cancer regrowth and metastasis in cells that survived chemotherapy." (PMID 26486085, 2015). "Accumulating evidence indicates that dysregulation of TLR4 is causally linked to tumor development and growth." (PMID 26514586, 2015). "This pathway and activated anti-tumor immunity play important roles in human cancer, as patients with breast cancer who carry a TLR4 loss-of-function allele relapse more quickly after radiotherapy and chemotherapy." (PMID 24686897, 2014). "The TLR4 gene contains two single-nucleotide polymorphisms (SNPs), namely, Asp299Gly and Thr399Ile that are significantly important in tumor development." (PMID 25076949, 2014). "In FTC, TLR4 was localized to inflammatory tissue regions surrounding the tumor and TLR4 expression was associated with metastasis in FTC patients." (PMID 24723911, 2014). "Release of HSP from tumor cells can lead to activation of TLR4 on tumor-associated macrophages, in turn mediating NF-κB activation of tumor cells." (PMID 25309546, 2014). "Others using different methodology and smaller numbers demonstrated that TLR4 is associated with tumor stage." (PMID 24887394, 2014). "As TLR4 is functionally associated with tumor progression, TLR4 is likely to be a promising target for tumor therapy in the future." (PMID 24527095, 2014). "More interestingly, we found that there was a tendency that expression of TLR4 in tumor tissues increased in association with lymph node metastasis." (PMID 25299052, 2014). "When released, S100A8/A9 can signal through the receptor for advanced glycation end products (RAGE) and toll-like receptor 4 (TLR4) to promote tumor-associated inflammation and progression of advanced stage adenocarcinomas and colitis-associated cancer." (PMID 23874958, 2013).
tumor (continued). "All these data indicate that expression of TLR4 or CXCR7 is associated with PTC tumor size and lymph node metastasis." (PMID 24363762, 2013). "In a recent publication, we investigated the impact of S100A9- and TLR-4 deficiency on tumor growth in the TRAMP prostate cancer model." (PMID 23234398, 2012). "The co-expression of TLR4/MyD88 or TLR4/MyD88/NF-κB was significantly associated with tumor stage and histologic type." (PMID 22985132, 2012). "We found that TLR4, MyD88 and N-FκB were frequently expressed in tumor cells of OECs and that expression of TLR4, MyD88, TLR4/MyD88 and TLR4/MyD88/NF-κB was associated with overall survival in patients with OECs." (PMID 22985132, 2012). "Our studies indicate that autophagy activation in tumor cells from the mice treated prophylactically with the TLR4/9 agonist complex is associated with the elevated levels of IFNγ expression and STAT1 phosphorylation." (PMID 21931823, 2011). "Additional alternative therapeutic approaches are based on combination of TLR4 agonist as a vaccine adjuvant with tumor-associated antigens in combination with radio- or chemotherapy or autologous dendritic cell therapy." (PMID 22110526, 2011). "Accordingly, tumor-bearing TLR4 deficient mice had reduced responses to chemotherapy and radiation therapy compared to WT mice." (PMID 22069563, 2010). "The tumor incidence caused by TLR4 transduction and LPS injections was reduced by coexpression of short hairpin RNA against Nanog, indicating that Nanog expression is involved in tumor formation and growth in this model." (PMID 20827314, 2010). "We believe that TLR4 activation induces other tumor-driver genes which cooperatively work with Nanog to cause liver oncogenesis." (PMID 21331379, 2010). "Interestingly, although TLR4 signalling in cancer cells and tumour-associated macrophages leads to different activation outputs, they can both induce gelatinases through NF-κB, MAPK, and Akt pathways." (PMID 42121921, 2026). "Conversely, tumors with high PD‐L1 levels may suppress the inflammatory pathways associated with TLR4 to establish an immune‐tolerant environment conducive to tumor growth." (PMID 40762187, 2025). "For example, some small-molecule agonists may activate TLR-4 in non-tumor cells, leading to unwanted immune activation and associated side effects." (PMID 40404908, 2025). "Supporting these observations, previous studies have shown that CCRL2 can modulate innate immune signaling via direct interactions with receptors such as TLR4, enhancing its plasma membrane stability and promoting MyD88-dependent NF-κB signaling in tumor-associated macrophages." (PMID 40867595, 2025). "High TLR4 expression significantly correlated with perineural invasion (30.0% vs 5.6%, p=0.029), with trends toward association with vascular invasion (17.6% vs 6.0%, p=0.123) and high-grade tumor budding (18.8% vs 5.4%, p=0.161)." (PMID 40703545, 2025). "Among the 10 identified TLRs, TLR4 is linked to tumor progression and antitumor immunity." (PMID 40762187, 2025). "Moreover, TLR4 gene deficiency produced a caspase-3-dependent apoptotic mechanism, that inhibited tumor growth." (PMID 40727443, 2025). "According to a different study, TLR4 deficiency prevented the growth of U87 tumor xenografts." (PMID 40727443, 2025). "Moreover, elevated LPS result from gut microbiota imbalance has been implicated in the secretion of cathepsin K (CTSK), which further promotes CRC metastasis by stimulating M2 polarization of tumor-associated macrophages (TAMs) through the TLR4/mTOR pathway." (PMID 40181829, 2025).
tumor (continued). "However, under chronic high‐dose HMGB1 exposure or specific TLR4 polymorphisms, the HMGB1‐TLR4 signal instead inhibits phagosome‐lysosome fusion, reduces tumor antigen cross‐presentation, and causes failed CD8+ T cell priming." (PMID 41354099, 2025). "PD‐L1 expression on oral tumor cells may adaptively respond to TLR4‐mediated inflammation, causing CD8+ TIL exhaustion and immune evasion." (PMID 40762187, 2025). "Moreover, ADCs polarize tumour-associated macrophages (TAMs) towards pro-inflammatory M1 phenotypes by upregulating toll-like receptor 4 (TLR4) and suppressing scavenger receptor class A member 5 (SCARA5), thereby enhancing phagocytosis and IL-12 secretion." (PMID 40909270, 2025). "Of note is the plethora of studies that have implicated TLR4 in the progression of tumor cells." (PMID 40124677, 2025). "The TRAF6/NF-κB pathway was linked to TLR4’s role in tumor progression." (PMID 38315263, 2024). "Given that high TLR4 expression is associated with increased metastasis and invasion of tumor cells, targeting TLR4 signaling pathways could be a viable strategy for treatment." (PMID 39026223, 2024). "Tumor cells expressing TLR4 are linked to decreased recurrence rates, while fibroblasts expressing TLR4 are independently associated with higher recurrence rates and shorter overall survival, suggesting fibroblast TLR4 expression as a prognostic marker in CRC." (PMID 38930793, 2024). "This miRNA regulates different pathways, including cell proliferation, apoptosis, and inflammatory cascades; it is implicated in immune-related disorders, through TLR4/NF-κB signaling modulation, and has been found to be downregulated in several neoplastic diseases." (PMID 37445763, 2023). "TLR-4 expression was associated to a larger tumor size and a higher HCC grade, suggesting that it could be used to predict HCC prognosis." (PMID 35867269, 2023). "Alternatively, research establashing LPS as pro-tumor largely employimmune deficient models such as nude mice, cancer cells without an immune co-culture, or by general expression profile that shows TLR4 to be abundant in malignant tumor tissue relative to normal." (PMID 37654434, 2023). "In addition to its role in the innate immune system, TLR4 has also been implicated in adaptive immunity, including specific anti-tumor immune responses." (PMID 37345131, 2023). "Second, chemotherapeutically treated dying tumor cells release damage-associated molecular patterns such as hypermobility group box 1, which can be recognized by Toll-like receptor 4 (TLR4) to promote dendritic cell maturation and activation and enhance the antitumor T-cell response." (PMID 36979400, 2023). "Moreover, TLR-4 expressed on tumor-associated macrophages (TAM) is responsible for the migration of the TAMs into the TME." (PMID 37630236, 2023). "In addition, increased TLR4 expression was associated with liver metastasis (P = 0.0015) and advanced tumor stage (stage IV) (P = 0.0197)." (PMID 35841426, 2023). "The MyD88, for instance, is an essential adaptor protein for Toll-like receptor (TLR) signaling, which can suppress M2 gene expression in tumor-associated macrophage (TAMs) and promote tumoricidal M1 phenotype through the activation of TLR4/MyD88/NF-κB pathway." (PMID 37476181, 2023). "Moreover, nodal metastasis tended to be associated with low levels of CD69, MYD88, and TLR4 mRNA expression within the tumor (p = 0.11, p = 0.06, and p = 0.06, respectively)." (PMID 36281585, 2023). "In conclusion, our present study authenticated that the F. nucleatum-derived EVs manifested a promotive function on tumor growth and metastasis of BC, which might be associated with its role in TLR4 activation." (PMID 37221488, 2023). "Moreover, chronic sleep restriction can accelerate carcinogenesis and tumor growth in a mouse model mediated by immunological mechanisms, such as tumor-associated macrophages and toll-like receptor 4 (TLR4) signaling." (PMID 36290905, 2022).
tumor (continued). "Indeed, F. nucleatum has been reported to promote chemoresistance in CRC patients through loss of tumor-suppressive miR-18a* and miR-4802 by activating TLR4/MyD88-dependent signaling." (PMID 35625485, 2022). "On the other hand, this study suggests that the activation of TLR-4 in tumor associated macrophages, which affects their polarization, is influenced by microenvironmental cues and may significantly impact on tumor growth and progression." (PMID 35148799, 2022). "TLR2 and TLR4 in a double knockout metastatic lung cancer model have been shown to influence the ability of the tumor to proliferate and grow, as well as to decrease the number of neutrophils associated with the tumor." (PMID 36389785, 2022). "Furthermore, the upregulation of TLR4 was associated with a different histologic type and tumor progression." (PMID 36231099, 2022). "Thus, our data consistently demonstrated that TLR4 proficient macrophages promoted while TLR4 deficient macrophages impeded tumor progression." (PMID 36542153, 2022). "Taken together, these data suggest that in OSCC F. nucleatum may be associated with “permissive” tumor microenvironment, insensitive to pro-inflammatory signals, with low TLR4 signaling and low recruitment of M2, resulting in favorable clinical outcomes." (PMID 33846399, 2021). "Diverse studies have shown that TLR4 is associated with tumor development and progression." (PMID 33733435, 2021). "Additionally, TLR activation such as TLR4 is linked to angiogenesis, tumour proliferation and immune evasion." (PMID 32391647, 2020). "Another study that analyzed 116 tissue samples from patients with different stages of colorectal disease found that patients with higher TLR4 tumor expression levels had a greater risk of disease progression and relapsed earlier than those with lower expression levels." (PMID 32095158, 2020). "TLR4 associated with gender (p = 0.006) and the tumor grade (p < 0.001, chi-square test)." (PMID 32424768, 2020). "Indeed, a number of studies have implicated TLR4 to be involved in key growth and antiapoptotic signaling mechanisms in tumor cells." (PMID 33073533, 2020). "HSP60 was also reported to interact with and activate β-catenin, and can act as a ligand to Toll like receptor 4 (TLR4) that can activate the NF-κB pathway which is implicated in tumor development through creating a state chronic inflammation that favor tumor growth." (PMID 32466334, 2020). "We may speculate that early IgM production, activated three days post infection, may be linked to a role of TLR4, as it was recently shown that B1 cell activation and tumor-reactive IgM production were defective in TLR4KO mice." (PMID 33519799, 2020). "Furthermore, TLR4 gene deficiency induced apoptosis process (caspase-3-dependent), resulting in a decrease in tumor growth." (PMID 31240216, 2019). "Increasing data proposes that the initiation of TLR2/TLR4 signaling enhances tumor cell growth, downregulates apoptosis, and upregulates the synthesis of growth factors and inflammation-associated cytokines by tumor and stromal cells." (PMID 31068944, 2019). "To better understand if the gene deficiency of TLR-4 could increase the expression of Dkk-3, we made an immunoistochemical analysis of Dkk-3 and claudin-5 on tumor sections." (PMID 30680070, 2018). "TLR4, a cell membrane receptor, has also been implicated in tumor promotion." (PMID 29416610, 2018). "Thus, TLR4 deficiency impairs this platelet-tumor cell interaction and suppresses experimental lung metastases." (PMID 29636841, 2018). "We postulated that TLR4 knockout prevents the increase in circulating cytokines that could stimulate muscle catabolism such as TNFα, IL-6 and IL-1β, and determined the effect of TLR4 deficiency on circulating cytokines in LLC tumor-bearing mice." (PMID 28536426, 2017). "Furthermore, several preclinical studies showed that mice deficient in TLR4 are markedly protected against colitis associated neoplasia." (PMID 28408791, 2017).